INS (insulin)
Diseases named in the same sentence as INS in open-access papers (continued):
Sharing a sentence is not in itself a finding about the gene and the disease.
Insulin resistance (continued). "In GDM, the alterations in maternal metabolism that emerge during the second trimester can blunt insulin signaling and sensitivity, which leads to increased insulin resistance and glucose intolerance." (PMID 41003859, 2025). "Insulin resistance (IR) is a pathological condition in which the target organs of insulin action are hypersensitive to insulin; in other words, a normal insulin dose delivers less than the normal biological effect." (PMID 40583967, 2025). "In subjects with insulin-resistance, pancreatic insulin secretion is increased, both in the fasting and postprandial phases, since peripheral tissues require higher concentrations of insulin for glucose uptake." (PMID 40097487, 2025). "We have also examined the hepatic insulin resistance by performing Western blot analysis after insulin injection." (PMID 41163804, 2025). "Hyperinsulinemia refers to an elevated level of circulating insulin (80 and 100 μU/mL), often leading to metabolic disorders such as obesity, insulin resistance, and type 2 diabetes (T2D)." (PMID 40868096, 2025). "Specifically, the presence of FFA activates the NOX pathway in adipose tissue, enhancing ROS production, which exacerbates oxidative damage and affects insulin signaling pathways, leading to increased insulin resistance." (PMID 40599237, 2025). "Such glucolipotoxicity is known to induce insulin resistance and neurotoxicity in these cells, where palmitate reduces insulin-induced signaling, and increases inflammatory cytokine expression, oxidative stress, and apoptosis." (PMID 39773760, 2025). "We have focused mainly on studies investigating insulin resistance by the gold-standard technique, the glucose–insulin clamp, which allows comparison of individuals with T1D with glucose-tolerant humans at identical glycemia and insulinemia." (PMID 39998445, 2025). "Significantly, we observed a substantial improvement in insulin resistance, a crucial pathological indicator used to assess glucose metabolism efficiency and insulin sensitivity in individuals with T2DM." (PMID 39949529, 2025). "RS disrupts insulin secretion and signaling, exacerbates metabolic inflammation, and contributes to adipose tissue dysfunction, ultimately promoting insulin resistance." (PMID 40076537, 2025). "Insulin resistance naturally increases during pregnancy and maternal tissues become increasingly insensitive to insulin as gestation advances, with a 50%–60% decrease in insulin sensitivity both in women with normal glucose tolerance and in women with GDM." (PMID 40618386, 2025). "Quinones can improve insulin resistance and regulate glucose homeostasis by modulating mitochondrial function, inflammation, lipid profile, gastrointestinal absorption, and by acting as insulin mimetics." (PMID 39942768, 2025). "We calculated index of Homeostasis Model Assessment 2 (HOMA2-%S) and HOMA IR and found decreased insulin sensitivity but increased insulin resistance in KO mice fed with normal diet, compared to the control mice." (PMID 41234234, 2025). "This inflammation can interfere with insulin signaling, worsening insulin resistance and contributing to the development of type 2 diabetes." (PMID 40564010, 2025). "Misfolding of proinsulin in the endoplasmic reticulum contributes to β-cell dysfunction, potentially impairing the quality of insulin secretion and promoting the development of hyperinsulinemia, which in turn leads to insulin resistance." (PMID 40868096, 2025). "If insulin action is impaired, a wide range of systemic abnormalities, beyond glucose, can be observed, allowing for the prediction of abnormalities in insulin resistance." (PMID 39815341, 2025). "In general, most studies support the idea that inhibiting LPCAT3 offers benefits in strengthening insulin signaling, alleviating insulin resistance, and improving glucose tolerance." (PMID 40737292, 2025). "Excessive mitochondrial ROS directly suppresses insulin signal transduction, promoting insulin resistance." (PMID 41226411, 2025).
Insulin resistance (continued). "Secondly, plant heteropolysaccharides modulate insulin-related signalling pathways to ameliorate insulin resistance, thereby preserving systemic glucose homeostasis." (PMID 40729002, 2025). "Insulin-sensitive cells from different organs and tissues trigger an impairment of the insulin signaling pathway when they develop insulin resistance." (PMID 40076851, 2025). "This proinflammatory state, and the imbalanced immunoreaction, has been proposed to contribute to insufficient insulin synthesis and insulin resistance." (PMID 40901355, 2025). "Various IF regimens have shown promise in reducing fasting insulin, insulin resistance, and HbA1c levels in healthy individuals with obesity and prediabetes." (PMID 40533648, 2025). "As expected, participants with T2D exhibited low insulin sensitivity and high whole-body and adipose tissue insulin resistance." (PMID 40797027, 2025). "Animals with insulin resistance fail to respond effectively to insulin and, consequently, exhibit elevated blood glucose concentrations." (PMID 40108709, 2025). "Over 30 y ago, elegant studies from DeFronzo’s group showed that a 72 pmol/L increase in serum insulin sustained for 3 d induced insulin resistance and reduced whole body glucose disposal and the ability of hyperglycemia to induce insulin secretion." (PMID 41439105, 2025). "Insulin resistance is a prevalent clinical condition, typically defined as a pathological state in which the biological response to normal insulin concentrations is subnormal." (PMID 41586243, 2025). "Other clinical studies have aimed to untangle the role of insulin resistance in CAC using fasting insulin as a surrogate measure, but the findings are inconclusive and inconsistent." (PMID 41367198, 2025). "Hyperglycemia and elevated free fatty acids trigger the release of pro-inflammatory mediators and oxidative stressors, which, in turn, promote insulin resistance and impair insulin release by pancreatic β-cells." (PMID 41003859, 2025). "The typical symptoms of DN were high BG and urea, gamma-GT, HDL-C, and creatinine concentrations resulting from insulin resistance, impaired insulin secretion, and acute kidney failure." (PMID 40182806, 2025). "It has also been established that Serpin B1 and NE can mediate insulin signaling and the development of insulin resistance." (PMID 41340462, 2025). "Physicians select drugs considering insulin secretion and insulin resistance, age, obesity, severity of chronic complications, and liver and kidney function." (PMID 40456113, 2025). "And insulin resistance impairs the body's ability to use insulin effectively, leading to reduced bone formation by inhibiting collagen synthesis and osteoblast activity." (PMID 41013763, 2025). "Ancestry-specific differences in the balance between insulin secretion and insulin resistance further contribute to T2D heterogeneity." (PMID 41001674, 2025). "Central insulin resistance further strengthens the link to neurodegenerative pathology by impairing brain insulin signaling, which is crucial for glucose metabolism, synaptic plasticity, neuronal survival, and cognitive function." (PMID 40283923, 2025). "Muscle insulin resistance is the earliest detectable abnormality, prompting the pancreas to increase insulin production to maintain glucose balance." (PMID 41155203, 2025). "Peripheral insulin resistance (IR) in T2DM disrupts central insulin signaling through various mechanisms, leading to neurodegeneration." (PMID 40896190, 2025). "In recent years, the role of the gut microbiota in regulating glucose metabolism, maintaining insulin sensitivity, and mediating insulin resistance has emerged as a major focus of research." (PMID 41357185, 2025). "Although housing did not affect plasma insulin concentration during the OGTT, males had higher insulin concentrations than females, indicating potential insulin resistance in male rats." (PMID 39821966, 2025).
Insulin resistance (continued). "Raised fasting glucose in the adults suggested insulin resistance, and more detailed experiments to assess insulin signalling in the tissues and in-vivo responses to a range of insulin doses would help to clarify mechanisms." (PMID 40682692, 2025). "There are various methods for clinically assessing insulin resistance (IR), with the insulin clamp and glucose tolerance tests widely recognized as frequently used standards for measuring peripheral insulin sensitivity." (PMID 40800025, 2025). "Moderate ERK1/2 activation can promote insulin secretion and synthesis, while excessive activation can lead to insulin resistance and even lead to islet β cell dysfunction." (PMID 40417223, 2025). "Previous studies have reported that HIIT lowers fasting glucose and improves insulin sensitivity in adults with obesity, mitigates insulin resistance in sedentary older populations, and enhances glycemic control in women." (PMID 41367390, 2025). "This fasting state, which is largely influenced by the basal state, is also used as a measure of insulin secretion and insulin resistance and predicts the response to non-insulin treatments for T2DM." (PMID 40428172, 2025). "Under diabetic conditions, insufficient insulin secretion or insulin resistance impairs glucose utilization, prompting the body to metabolize fats for energy, resulting in elevated serum TC and TG levels." (PMID 40708699, 2025). "This disruption results in diminished insulin-mediated glucose uptake and contributes to the development of insulin resistance." (PMID 40626240, 2025). "Instead, some evidence suggests that delivery of insulin across the blood-brain barrier is disrupted with increasing insulin resistance." (PMID 39185744, 2025). "Dysfunction of these signaling pathways frequently leads to insulin resistance, which limits the physiological effects of insulin and impairs blood glucose control." (PMID 39941934, 2025). "It has the function of enhancing GLu‐dependent insulin secretion, inhibiting glucagon secretion, slowing gastric emptying to reduce blood GLu, and alleviating insulin resistance." (PMID 40078029, 2025). "It is a reflect of the severity of insulin secretory defects and/or insulin resistance, but also a poor control of maternal glucose levels." (PMID 41237113, 2025). "A shift in the cellular redox state toward oxidation reduces the overall activity of serine/threonine phosphatases, which enhances the activity of stress-sensitive serine/threonine kinases and suppresses insulin signaling, thus promoting insulin resistance." (PMID 39966707, 2025). "T2DM is characterised by chronic hyperglycaemia due to a combination of insulin resistance and insufficient insulin secretion from the β-cells of the pancreatic islets." (PMID 40332335, 2025). "The disease is characterized by impaired insulin secretion from pancreatic β-cells and peripheral insulin resistance." (PMID 41438030, 2025). "For instance, in rodent models of metabolic-associated fatty liver disease (MAFLD) and obesity-related insulin resistance, PFD administration improved insulin sensitivity, reduced hepatic steatosis, and attenuated pro-inflammatory signaling pathways." (PMID 40587406, 2025). "Adipokines, cytokines secreted by adipose tissue, which sensitize insulin, such as adiponectin, on the other hand, counteract insulin resistance." (PMID 41012462, 2025). "Elevated levels of DAG have been implicated in the activation of protein kinase C (PKC), which can interfere with insulin signaling pathways, thereby contributing to insulin resistance and the development of T2DM." (PMID 40862129, 2025). "In turn, excess weight gain promotes insulin resistance, which leads to higher exogenous insulin requirements." (PMID 40004833, 2025). "Insulin resistance (IR), characterized by diminished cellular response to insulin, leads to compensatory hyperinsulinemia." (PMID 41567806, 2025).
Insulin resistance (continued). "Insulin resistance further exacerbates these effects by triggering the overproduction of insulin, which drives inflammatory cytokines and impairs endothelial function, contributing to vascular damage." (PMID 40227756, 2025). "Luteolin and its glycoside derivative significantly improve glycemic parameters (fasting glucose, HbA1c, insulin levels, and homeostatic model assessment of insulin resistance) in diabetic KKAy mice, with luteolin outperforming its glucosylated form." (PMID 40647154, 2025). "MSCs can differentiate into insulin-producing cells (IPCs), promote the regeneration of pancreatic islet beta cells, protect endogenous islet cells, and improve insulin resistance, thereby exerting a positive impact on T2DM." (PMID 40565232, 2025). "The intraperitoneal glucose tolerance test and intraperitoneal insulin tolerance test showed mild insulin resistance." (PMID 41154683, 2025). "Human trials and mechanistic studies are recommended to investigate the efficacy of the extract in treating insulin resistance by evaluating fasting blood glucose, insulin levels, and HOMA-IR." (PMID 40541990, 2025). "IFN-γ can modulate the phosphorylation status of IRS through activation of the p38-MAPK signaling pathway, thereby disrupting insulin signaling and ultimately leading to insulin resistance." (PMID 40070584, 2025). "A key characteristic of muscle disuse is the rapid development of peripheral insulin resistance (i.e., impaired insulin‐stimulated muscle glucose uptake; measured as a 28% reduction in forearm glucose uptake), which precedes measurable muscle atrophy." (PMID 41194654, 2025). "Insulin and insulin resistance (IR) play a central role in the complex relationship between obesity and puberty, significantly influencing gonadal function through multiple pathways." (PMID 39941454, 2025). "In participants without previous history of T2D (Cohort 1), fasting glucose, insulin, and C-peptide levels, along with insulin resistance (HOMA2-IR), were negatively correlated with %TWL." (PMID 40687579, 2025). "This insulin resistance primarily affects the liver, muscle, and adipose tissue, resulting in a significant reduction in their sensitivity to insulin." (PMID 40430234, 2025). "The Tango2–/– mice were glucose intolerant, developed insulin resistance and had increased circulating levels of insulin on both diets." (PMID 40480980, 2025). "Insulin resistance (IR) can be defined as a state where abnormally high levels of insulin are needed to produce a normal response in target tissues." (PMID 41463398, 2025). "TFSE effectively reversed TNF-α-induced insulin resistance in 3T3-L1 adipocytes by enhancing insulin-stimulated glucose uptake, indicating anti-diabetic potential." (PMID 40807540, 2025). "Insulin resistance, which underlies T2DM, compromises glucose uptake in insulin-sensitive tissues such as the liver and adipose tissue." (PMID 40573083, 2025). "Insulin resistance (IR) is a pathological condition characterized by a diminished cellular response to insulin, requiring higher insulin levels to maintain normal glucose homeostasis." (PMID 40682200, 2025). "Insulin resistance is a decrease in the body’s sensitivity to insulin, leading to compensatory hyperinsulinemia, which is the core pathophysiological mechanism of various metabolic diseases." (PMID 40475963, 2025). "Accordingly, it is suggested that in insulin resistance, loss of AKT-mediated insulin signaling upregulates TSP1 expression in the vascular wall, contributing to VSMC transformation to inflammatory phenotypes." (PMID 40940776, 2025). "The third is to improve insulin resistance, restore insulin sensitivity, correct lipid metabolism, and reduce liver fat accumulation." (PMID 41169417, 2025). "Existing studies have clearly shown that STEAP4 deficiency leads to adipose tissue dysfunction, enhanced inflammation, and impaired insulin signaling, while overexpression can improve insulin resistance." (PMID 41317904, 2025).
Insulin resistance (continued). "The result is tissue-wide insulin resistance: insulin-stimulated glucose uptake is blunted, leading to compensatory hyperinsulinemia that further feeds ROS production (a vicious cycle)." (PMID 40694958, 2025). "Gut dysbiosis induces alterations in intestinal metabolites that lead to the development of insulin resistance by influencing insulin-sensitive organs and tissues." (PMID 39861118, 2025). "This creates a vicious cycle where iatrogenic hyperinsulinemia (related to intensive insulin therapy based on subcutaneously administered exogenous insulin) promotes insulin resistance and weight gain." (PMID 40004833, 2025). "The liver is responsible for clearing approximately 50%–60% of endogenous insulin during its first pass, but this amount is significantly reduced in youths with obesity and hepatic insulin resistance." (PMID 40365648, 2025). "Compounds such as quercetin and anthocyanins, present in P. domestica, are particularly effective in improving insulin signaling pathways, thereby mitigating insulin resistance, a major driver of MASLD progression." (PMID 40219006, 2025). "In summary, DHM and other natural compounds exhibit substantial potential for improving insulin resistance by targeting key regulatory nodes within the insulin signaling pathway and enhancing overall insulin sensitivity." (PMID 40740995, 2025). "Lower glucose levels support lower insulin levels, the sensitisation of body cells to this hormone, and reduced insulin resistance, which often accompanies obesity and overweight and hinders weight loss." (PMID 40289934, 2025). "Within the pancreas, insulin secretion and β-cell function are regulated by mTORC1, and its pathological regulation results in β-cell dysfunction and insulin resistance during obesity." (PMID 40218884, 2025). "During pregnancy, women frequently develop progressive insulin resistance, driven by rising maternal obesity rates and placental hormone-induced insulin desensitization." (PMID 40430234, 2025). "T2DM is defined as a chronic disturbance in glucose metabolism stemming from impaired insulin secretion, peripheral insulin resistance, or a combination of these pathophysiological processes." (PMID 40710007, 2025). "In vitro models of intestinal absorption and hepatic insulin resistance revealed a reduced glucose transport rate and enhanced glycogen accumulation, indicating potential improvements in insulin sensitivity." (PMID 41375973, 2025). "SIRD showed the highest HOMA-IR values with relatively intact insulin secretion, pointing to severe insulin resistance as the predominant defect." (PMID 41153348, 2025). "Insulin resistance is characterised by a diminished response to insulin stimulation in insulin-sensitive organs and tissues such as the liver, skeletal muscle, and adipose tissue." (PMID 41002997, 2025). "Cortisol is widely known to impair insulin sensitivity at multiple sites, including the liver, skeletal muscle, and adipose tissue, leading to whole-body insulin resistance." (PMID 40296149, 2025). "This post-translational modification contributes to the disruption of insulin signaling and the development of insulin resistance." (PMID 41294899, 2025). "It is important to note that most of these studies were conducted in patients whose pathogenesis of the disease was related to insulin resistance, so the results have shown progress in reducing insulin resistance and improving insulin sensitivity." (PMID 40142110, 2025). "This increase in body weight further exacerbates insulin resistance, diminishing peripheral tissue sensitivity to insulin and impairing the effective utilization and metabolism of glucose." (PMID 40386230, 2025). "VitD is effective in regulating insulin secretion and reducing insulin resistance by stimulating pancreatic β cells." (PMID 40105563, 2025).